SNHG3 (small nucleolar RNA host gene 3)
Diseases named in the same sentence as SNHG3 in open-access papers (continued):
Sharing a sentence is not in itself a finding about the gene and the disease.
breast cancer (continued). "Breast cancer derived CAFs secreted significantly increased SNHG3 than that of normal breast cells MCF10A." (PMID 31956955, 2020). "Together, these results suggest that the knockdown of CAF-secreted exosomal SNHG3 inhibited breast cancer cell proliferation through increasing miR-330 and decreasing PKM expression." (PMID 31956955, 2020). "The increase of ECAR when MDA-MB-453 cells overexpressing SNHG3 further confirmed that the alteration of glycolysis metabolism in breast cancer cells is dependent on CAF-secreted exosomal SNHG3." (PMID 31956955, 2020). "Then loss-of-function and gain-of-function assays were carried out to investigate the biological function of SNHG3 during the growth of breast cancer cells." (PMID 31956955, 2020). "CAF-derived exosomes deliver SNHG3 to breast cancer cells, serving as a molecular sponge suppressing miR-330-5p expression; promote breast cancer glycolysis and growth through PKM (miR-330-5p target) modulation." (PMID 32957712, 2020). "In this study, we provided evidences that the expression of SNHG3 was abnormally increased in breast cancer patients-derived CAFs." (PMID 31956955, 2020). "Functionally, SNHG3 knockdown hindered breast cancer cell proliferation, migration and invasion in vitro and in vivo." (PMID 33292213, 2020). "In summary, our results demonstrated that knockdown of CAF-secreted exosomal SNHG3 inhibited breast cancer glycosis and growth in vivo by upregulating miR-330 and downregulating PKM." (PMID 31956955, 2020). "Mechanistically, knockdown of exosomal SNHG3 suppressed breast cancer growth and glycolysis in vivo and in vitro through up-regulating miR-330 and decreasing the expression of PKM." (PMID 33077737, 2020). "In breast cancer cells, studies have revealed that HuR protein directly binds to SNHG3." (PMID 41042421, 2025). "An article examined SNHG3's role in breast cancer growth and metabolic reprogramming." (PMID 39349640, 2024). "A study investigated SNHG3's role in bone metastasis of breast cancer (BM-BCa)." (PMID 39349640, 2024). "The upregulation of SNHG3 in breast cancer underscores its potential as a therapeutic target." (PMID 39349640, 2024). "Similarly, another study revealed SNHG3 upregulation in breast cancer, enhancing CSNK2A1 expression by absorbing miR-485-5p and recruiting the HuR protein, thereby driving disease progression." (PMID 39349640, 2024). "Moreover, SNHG3 knockdown significantly repressed breast cancer cell growth both in vitro and in vivo." (PMID 37348024, 2023). "However, the precise biological roles and mechanisms through which SNHG3 contributes to breast cancer are poorly comprehended." (PMID 37348024, 2023). "Taken together, our study reveals a SNHG3-based regulatory network, which plays an oncogenic role in breast cancer and suggests that SNHG3 may serve as a potential target for the diagnosis and treatment of breast cancer." (PMID 37348024, 2023). "Through cellular biological experiments, SNHG3 was found to facilitate proliferation, migration, invasion, and cell cycle progress, and hinder cell apoptosis of PCa cells, which was congruous with its function in larynx carcinoma and breast cancer." (PMID 35123415, 2022). "Overall, SNHG3 could play a major role in the development and progression of breast cancer and support the therapeutic potential of targeting communication between cancer cells and tumor microenvironment." (PMID 31956955, 2020). "Collectively, these results indicated CAF-secreted exosomal SNHG3 could promote proliferation and downregulate mitochondrial function in breast cancer cells." (PMID 31956955, 2020). "However, the regulatory roles and the detailed mechanism of CAF-secreted exosomal SNHG3 in breast cancer remain poorly understood." (PMID 31956955, 2020). "Importantly, SNHG3 was identified as a potential oncogene in breast cancer based on previous studies which focused on cancer cell-autonomous function of SNHG3." (PMID 31956955, 2020).
breast cancer (continued). "Surprisingly, we found high expression of SNHG3 in exosomes secreted by CAFs isolated from breast cancer patients CAFs which may be important in the progression of breast tumor." (PMID 31956955, 2020). "Therefore, knockout mouse models with conditional deletion of SNHG3 or its target miR-330 were generated and under investigation in our lab to define the exact role of SNHG3/miR-330 signaling axis in breast cancer progression." (PMID 31956955, 2020). "By bioinformatics analysis and experimental validation, SNHG3 could sponge miR-330 to promote the growth and regulate the metabolism of breast cancer cells." (PMID 31956955, 2020). "Similarly, SNHG3 expression was dramatically elevated in breast cancer cells and tissues, while overexpression of SNHG3 in MCF-7 band MDA-MB-231 cells induced breast cancer cell proliferation, EMT, migration, and invasion, through regulating miR-186-5p and ZEB1 expression." (PMID 36139687, 2022). "Moreover, miR-330-5p targeted PKM and regulated by SNHG3 in breast cancer cells." (PMID 33077737, 2020). "In our study, we explored both the expression patterns and biological functions of breast cancer derived CAF-secreted exosomal SNHG3 on breast tumor cells, as well as the molecular mechanism of SNHG3 during the development of breast cancer." (PMID 31956955, 2020). "Further investigation, including the identification of novel targets of SNHG3, will be needed to define the comprehensive role of CAF-secreted exosomal SNHG3 in breast cancer." (PMID 31956955, 2020). "Moreover, PKM could be targeted by miR-330-5p and was controlled by SNHG3 in breast cancer cells." (PMID 31956955, 2020). "For example, SNHG3 which was involved in the miR-186-5p/ZEB1 pathway could mediate pathological invasion and metastasis as well as transforming breast cancer cells into epithelial-mesenchymal." (PMID 38960931, 2024). "In the cytoplasm, SNHG3 facilitated the expression of Casein kinase II-A1 (CSNK2A1) by absorbing miR-485-5p and recruiting the HuR protein, participating in the malignant progression of breast cancer." (PMID 37348024, 2023). "In this study, SNHG3 was mainly detected in the cytoplasm of PC3 and C4-2B cells, indicating that SNHG3 may promote the development of PC by interacting with miRNA, which is also supported by previous findings on osteosarcoma, acute myeloid leukemia, breast cancer, liver cancer and gastric cancer." (PMID 35030969, 2022).
osteosarcoma (24 papers, 2019 to 2025). A usually aggressive malignant bone-forming mesenchymal neoplasm, predominantly affecting adolescents and young adults. "In osteosarcoma, SNHG3 expression is positively associated with tumor growth, whereas knockdown of SNHG3 remarkably reduces the viability and clone-forming ability of tumor cells." (PMID 39641310, 2024). "Elevated SNHG3 levels were significantly associated with poor OS in bladder cancer, clear cell renal cell carcinoma, colorectal carcinoma, gastric cancer, osteosarcoma, and ovarian cancer." (PMID 41042421, 2025). "For instance, elevated SNHG3 promotes osteosarcoma cell invasion and metastasis by regulating the miR-151a-3p/RAB22A signaling axis." (PMID 41234719, 2025). "For example, SNHG3 upregulates Ras-related protein 22a (Rab22a) by sponging miR-151a-3p, thereby promoting migration and invasion in osteosarcoma." (PMID 39349640, 2024). "High expression of SNHG3 correlated with reduced survival rates and heightened invasive and migratory abilities in osteosarcoma cells." (PMID 39349640, 2024). "For instance, emerging evidence shows that SNHG3 is a novel oncogenic lncRNA that is abnormally expressed in various types of tumor, including osteosarcoma, liver cancer and lung cancer." (PMID 36330438, 2022). "It has been reported that SNHG3 promotes the overexpression of Rab22a by regulating miRNA-151A3p in osteosarcoma, thereby promoting the invasion and migration potentials of osteosarcoma cells." (PMID 35757470, 2022). "A previous study demonstrated that the SNHG3/miRNA-151a-3p/Rab22a axis regulates invasion and migration of osteosarcoma." (PMID 33292213, 2020). "For instance, SNHG3 sponges miR-151a-3p as a ceRNA to upregulate Ras-related protein 22a (Rab22a) expression, thus increasing cell migration and invasion of osteosarcoma cells." (PMID 33292213, 2020). "Meanwhile, a recent article has indicated that overexpressed SNHG3 encouraged osteosarcoma (OS) cell invasion and migration, lessening the survival rate of OS patients." (PMID 32883233, 2020). "Emerging evidence shows that SNHG3 is a novel oncogenic lncRNA that is abnormally expressed in various tumors, including osteosarcoma, liver cancer, lung cancer, etc." (PMID 33292213, 2020). "For example, SNHG3 sponged miRNA-151a-3p and miR-196a-5p (Chen, Wu & Zhang, 2019) in order to promote cell growth, invasion, and migration in osteosarcoma." (PMID 31695969, 2019). "In osteosarcoma and bladder cancer, SNHG3 acts as an oncogenic factor; whereas in thyroid cancer, SNHG3 may function as a tumor suppressor gene by negatively regulating the AKT/mTOR and MAPK/ERK signaling pathways." (PMID 41234719, 2025). "In osteosarcoma, SNHG3 could promote the progression of SNHG3 by absorbing miRNA-151a-3p and then upregulating RAB22A expression." (PMID 33596916, 2021). "For instance, upregulation of SNHG3 indicates poor survival since SNHG3 could accelerate cell growth by sponging miR-196a-5p in osteosarcoma patients." (PMID 33817254, 2020). "SNHG3 forms an SNHG3/miRNA‐151a‐3p/RAB22A pathway to regulate the cell migration in osteosarcoma." (PMID 32248648, 2020). "The research focused on evaluating the expression levels of SNHG3, miRNA-151a-3p, and RAB22A, alongside assessing the invasive and migratory potentials of osteosarcoma cells." (PMID 39349640, 2024). "For example, overexpression of SNHG3 promoted the invasive and migratory potentials by targeting miRNA-151a-3p to enhance RAB22A expression in osteosarcoma." (PMID 33817254, 2020).
ovarian carcinoma (21 papers, 2019 to 2025). A malignant neoplasm originating from the surface ovarian epithelium. "Consistently, another study reported that SNHG3 expression was remarkably higher in ovarian cancer tissues than in adjacent normal tissues, and upregulating SNHG3 expression linked with poor prognosis and enhanced malignant progression of ovarian cancer." (PMID 32883233, 2020). "In ovarian cancer, SNHG3 promotes the expression of TRPC3 by interfering with miR−339-5p and then influences the cell cycle and subsequently inhibits tumor cell apoptosis." (PMID 41200835, 2025). "SNHG3 can regulate the development and progression of ovarian cancer cells and affect the diagnosis of ovarian cancer patients via the GSK3/β-catenin pathway." (PMID 41200835, 2025). "In ovarian cancer cells, inhibiting SNHG3 led to G1/G0 cell cycle arrest, suppressing malignant characteristics." (PMID 41042421, 2025). "B. Inhibition of Translation: In ovarian cancer (OC), SNHG3 regulates eukaryotic translation initiation factor 4A3 (EIF4A3) mRNA, implicating its role in energy metabolism and tumor progression." (PMID 39349640, 2024). "In ovarian cancer (OC), SNHG3 interacts with miR-139-5p and Notch1, promoting accelerated growth and migration." (PMID 39349640, 2024). "Overexpression of SNHG3 promoted the proliferation and invasion of ovarian cancer cells, resulting in a significant downregulation of CyclinD1, CDK1, MMP9 and MMP3." (PMID 33292213, 2020). "For instance, SNHG3 is related to energy metabolism by regulating eukaryotic translation initiation factor 4A3 (EIF4A3) mRNA in ovarian cancer (OC)." (PMID 33292213, 2020). "Lan Hong and his colleagues found that ovarian cancer cell proliferation and invasion were inhibited after SNHG3 knockdown." (PMID 32883233, 2020). "In this study, we focused on the potential involvement of lncRNA SNHG3 in GC, which previously has been intensively investigated in lung cancer, liver cancer and ovarian cancer, whereas greatly underappreciated in GC." (PMID 31534128, 2019). "After silencing SNHG3, the expression of some metastasis-related proteins, including CDK1, MMP3, and MMP9, is evidently reduced, suggesting that SNHG3 influences protein expression in ovarian cancer tissues to affect the migration and metastasis of tumor cells." (PMID 41200835, 2025). "In addition, SNHG3 interferes with miR−139-5p and then promotes the expression of Notch1 to promote the occurrence and development of ovarian cancer, thus serving as a proto-oncogene." (PMID 41200835, 2025). "A study investigated SNHG3 in ovarian cancer (OC), focusing on its role in disease progression." (PMID 39349640, 2024). "Additionally, increased SNHG3 was associated with poor progression-free survival (PFS) in bladder cancer, metastasis-free survival (MFS) and bone metastasis-free survival (BMFS) in ovarian cancer." (PMID 41042421, 2025). "In conclusion, SNHG3 may serve as a novel target for the diagnosis and treatment of ovarian cancer." (PMID 33292213, 2020). "Among lncRNAs, we found SNHG3 and SNHG7 to be enriched in ovarian cancer stem cell exosomes." (PMID 39891297, 2025). "Similarly, we found lncRNAs, including Small Nucleolar RNA Host Gene 3 (SNHG3) and Small Nucleolar RNA Host Gene 7 (SNHG7), to be enriched in ovarian cancer stem cell exosomes, highlighting a potential role in stem cell-like properties and tumor aggressiveness." (PMID 39891297, 2025).
gastric cancer (17 papers, 2020 to 2025). A primary or metastatic malignant neoplasm involving the stomach. "In gastric cancer (GC), SNHG3 acts as an oncogene by modulating the miR-139-5p/MYB pathway, thereby driving proliferation, migration, and invasion." (PMID 39349640, 2024). "A. DNA Methylation: SNHG3 plays a crucial role in DNA methylation by interacting with methylases, thereby promoting gastric cancer progression through the methylation of genes such as mediator subunit 18 (MED18)." (PMID 39349640, 2024). "In conclusion, our study showed that lncRNA SNHG3 is highly expressed in gastric cancer tissues and cells." (PMID 35528235, 2022). "To corroborate the function of SNHG3 targeting miR-448 in gastric cancer cells, we inhibited miR-448 (inh miR-448) in cells transfected with si-SNHG3." (PMID 35528235, 2022). "The results demonstrated that SNHG3 was upregulated, and miR-448 was downregulated in the gastric cancer tissue samples." (PMID 35528235, 2022). "In this study, we aimed to explore the clinical relevance and mechanistic role of SNHG3 in gastric cancer (GC)." (PMID 34898477, 2021). "For example, SNHG3 was significantly dysregulated in thyroid carcinoma 26, lung cancer 27 and gastric cancer." (PMID 33442418, 2021). "For instance, SNHG3 promotes gastric cancer progression through regulating neighboring mediator subunit 18 (MED18) gene methylation by binding to enhancer of zeste homolog 2 (EZH2)." (PMID 33292213, 2020). "The CCK-8 assay proved that SNHG3 knockout suppressed the growth of gastric cancer cells." (PMID 35528235, 2022). "The anticancer effect of MED18 occurs downstream of SNHG3 signaling in gastric cancer, which may imply its widespread mode of action in other cancers, and deserves further study." (PMID 33292213, 2020). "SNHG3 promoted the proliferation of gastric cancer cells both in vitro and in vivo." (PMID 33292213, 2020). "To explore how SEPT9 methylation is regulated by SNHG3 in gastric cancer, we transfected SNHG3-specific siRNA (si-SNHG3) or control siRNA (si-NC) into the GC cell lines HGC-27 and MGC-803." (PMID 35528235, 2022). "Our study investigated the mechanism of SNHG3 regulation of SEPT9 methylation and its effects on the growth, metastasis, and spread of gastric cancer cells." (PMID 35528235, 2022). "The results proved that miR-448 can interact with SNHG3 to participate in SEPT9 methylation, inhibit miR-448 to promote SEPT9 methylation, and restore gastric cancer cell growth, metastasis, and spread." (PMID 35528235, 2022). "Our study indicates that SNHG3 regulates SEPT9 methylation by targeting miR-448/DNMT1 and subsequently affecting the occurrence and development of gastric cancer." (PMID 35528235, 2022). "Although we confirmed in vitro that the SNHG3/miR-448/DNMT1 molecular axis mediates SEP9 methylation and thus affects the progression of gastric cancer, this study was limited in its ability to further verify this molecular mechanism in vivo." (PMID 35528235, 2022). "We found that SNHG3 was upregulated in gastric cancer and that SNHG3 knockdown or miR-448 overexpression inhibited SEP9 methylation and therefore increased its expression, thereby inhibiting the growth, metastasis, and spread of gastric cancer cells." (PMID 35528235, 2022). "We knocked out SNHG3 to inhibit the expression level of DNMT1 by regulating miR-448, which inhibits the methylation of SEPT9 mediated by DNMT1, upregulates the expression level of SEPT9, and prevents the invasion, metastasis, and spread of gastric cancer cells." (PMID 35528235, 2022). "However, the role of SNHG3 and its regulated miRNAs in the course of gastric cancer has not been elucidated." (PMID 35528235, 2022). "Therefore, we speculate that SNHG3 may regulate SEPT9 methylation through miR-448, thereby regulating the progression of gastric cancer." (PMID 35528235, 2022).
lung carcinoma (17 papers, 2018 to 2025). "The results demonstrated that CCDC26 and IFNG-AS1 may be new biomarkers for lung cancer, SNHG3 may be associated with PDL1 for lung cancer, and HOTAIR and BDNF-AS may be potential biomarkers for neuroblastoma." (PMID 37655066, 2023). "Case studies demonstrate that CCDC26 and IFNG-AS1 may be new biomarkers of lung cancer, SNHG3 may associate with PDL1 for lung cancer, and HOTAIR and BDNF-AS may be potential biomarkers of neuroblastoma." (PMID 37655066, 2023). "Furthermore, AI has shown that new biomarkers, such as CCDC26 and interferon gamma antisense RNA 1 (IFNG-AS1), may be related to lung cancer and Small Nucleolar RNA Host Gene 3 (SNHG3) may be associated with PD-L1." (PMID 40075729, 2025). "The results show that SNHG3 has a higher interaction probability with PDL1 and has been reported to be associated with lung cancer." (PMID 37655066, 2023). "For example, E2F transcription factor 1 (E2F1)-mediated transcriptional upregulation of SNHG3 in lung cancer enhanced the abilities of cell proliferation and migration by activating the TGF-β pathway and interleukin 6 (IL-6) signaling." (PMID 35030969, 2022). "SNHG3 is overexpressed in lung cancer tissues and cells, and a lot of studies have suggested that SNHG3 can affect the prognosis of LUAD through multiple pathways." (PMID 36387240, 2022). "Considering these findings, we conducted a subgroup analysis based on the expression level of SNHGs in lung cancer, and the results showed that low expression of SNHG2 and SNHG3 predicted a poor prognosis for lung cancer, while high expression predicted a poor prognosis for lung cancer." (PMID 38104110, 2023). "NONCODE data showed that SNHG3 expression was significantly higher in the thyroid gland, lymph node, adrenal gland, and lungs, suggesting that SNHG3 may play a key role in lung cancer progression." (PMID 30154938, 2018). "Second, additional molecular investigations of SNHG3 in lung cancer was still needed." (PMID 30154938, 2018). "SNHG2, SNHG3, and SNHG10 are expressed at low levels in lung cancer tissues, while other SNHGs are upregulated in lung cancer tissues." (PMID 38104110, 2023).